MAVS (mitochondrial antiviral signaling protein)
Description:
Adapter required for innate immune defense against viruses. Acts downstream of DHX33, RIGI and IFIH1/MDA5, which detect intracellular dsRNA produced during viral replication, to coordinate pathways leading to the activation of NF-kappa-B, IRF3 and IRF7, and to the subsequent induction of antiviral cytokines such as IFNB and RANTES (CCL5). Peroxisomal and mitochondrial MAVS act sequentially to create an antiviral cellular state. Upon viral infection, peroxisomal MAVS induces the rapid interferon-independent expression of defense factors that provide short-term protection, whereas mitochondrial MAVS activates an interferon-dependent signaling pathway with delayed kinetics, which amplifies and stabilizes the antiviral response. May activate the same pathways following detection of extracellular dsRNA by TLR3. May protect cells from apoptosis. Involved in NLRP3 inflammasome activation by mediating NLRP3 recruitment to mitochondria.
Synonyms: Cardif; IPS-1; VISA; IPS1; KIAA1271
Tractability: Antibody: UniProt predicts a signal peptide or a membrane-spanning region. PROTAC: UniProt records ubiquitination sites on it; ubiquitination databases record sites on it; its protein half-life has been measured.
Gene: Protein-coding gene on chromosome 20 (3,842,694 to 3,876,123, forward strand). Ensembl gene ENSG00000088888.
Subcellular location: Mitochondrion outer membrane; Mitochondrion; Peroxisome
Subcellular location (Human Protein Atlas): Mitochondria
Pathways (Reactome):
Immune System: DDX58/IFIH1-mediated induction of interferon-alpha/beta; NF-kB activation through FADD/RIP-1 pathway mediated by caspase-8 and -10; Negative regulators of DDX58/IFIH1 signaling; PKR-mediated signaling; TRAF3-dependent IRF activation pathway; TRAF6 mediated IRF7 activation; TRAF6 mediated NF-kB activation
Disease: Dengue virus activates/modulates innate and adaptive immune responses; Evasion by RSV of host interferon responses; SARS-CoV-1 activates/modulates innate immune responses; SARS-CoV-2 activates/modulates innate and adaptive immune responses
Metabolism of proteins: Ovarian tumor domain proteases
Gene Ontology:
Molecular function: CARD domain binding; DNA-binding transcription factor binding; identical protein binding; molecular adaptor activity; molecular condensate scaffold activity; protein binding; protein kinase binding; protein serine/threonine kinase binding; protein-macromolecule adaptor activity; signaling adaptor activity
Biological process: activation of innate immune response; antiviral innate immune response; cellular response to exogenous dsRNA; cellular response to interferon-beta; cytoplasmic pattern recognition receptor signaling pathway; defense response to bacterium; defense response to virus; innate immune response; intracellular signal transduction; negative regulation of viral genome replication; positive regulation of canonical NF-kappaB signal transduction; positive regulation of chemokine (C-C motif) ligand 5 production; positive regulation of defense response to virus by host; positive regulation of interferon-alpha production; positive regulation of interferon-beta production; positive regulation of interleukin-6 production; positive regulation of interleukin-8 production; positive regulation of IP-10 production; positive regulation of NLRP3 inflammasome complex assembly; positive regulation of protein import into nucleus; positive regulation of response to cytokine stimulus; positive regulation of transcription by RNA polymerase II; positive regulation of tumor necrosis factor production; positive regulation of type I interferon production; positive regulation of type I interferon-mediated signaling pathway; and 6 more
Cellular component: mitochondrial membrane; mitochondrial outer membrane; mitochondrion; peroxisomal membrane; peroxisome; ubiquitin ligase complex
Genetic constraint (gnomAD): Loss-of-function variants: 18 observed, 29.74 expected, observed/expected ratio (o/e) 0.61, 90% interval 0.42 to 0.9. The upper end of that interval is the gene's LOEUF score, 0.9, which puts it in group 3 of 6, group 1 being the genes least tolerant of losing a copy. Missense variants: 623 observed, 723.52 expected, observed/expected ratio (o/e) 0.86, 90% interval 0.81 to 0.92. Synonymous variants: 276 observed, 302.43 expected, observed/expected ratio (o/e) 0.91, 90% interval 0.83 to 1.01.
Homologues: Orthologues: macaque MAVS (91% identical), rabbit MAVS (58% identical), dog MAVS (54% identical), guinea pig MAVS (51% identical), pig MAVS (51% identical), mouse Mavs (49% identical), rat Mavs (48% identical), tropical clawed frog mavs (27% identical), zebrafish mavs (16% identical).
Diseases named in the same sentence as MAVS in open-access papers:
MAVS is named in the same sentence as 150 diseases in open-access papers, as found by Europe PMC text mining. Sharing a sentence is not in itself a finding about the gene and the disease. The quoted sentences say what the papers report.
viral infection (445 papers, 2008 to 2026). "Virus infection causes K63-linked ubiquitination of MAVS in the outer mitochondrial membrane and then induces aggregation of MAVS, which is a marker of its activation." (PMID 40016186, 2025). "Studies have reported that TRIM44 and OTUD4 can suppress the K48-linked polyubiquitylation of MAVS in response to virus infection." (PMID 40040697, 2025). "Viral infection has been shown to lead to K63-type linked ubiquitination of MAVS at the mitochondrial outer membrane which subsequently induces MAVS aggregation and activation." (PMID 40016186, 2025). "MAVS, crucial for antiviral responses, is associated with CA exacerbation, reflecting the role of viral infections in symptom severity." (PMID 40620703, 2025). "LRPPRC, a regulator of mRNA encoded by mitochondrial DNA, plays a significant role in viral infections by inhibiting antiviral signaling mediated by the mitochondrial antiviral-signaling protein (MAVS), acting as a suppressor in hepatitis C virus infection." (PMID 39622968, 2024). "K27-linked ubiquitination promotes RNA virus-induced MAVS activation and the innate immune response to viral infection." (PMID 37327222, 2023). "SERINC5 has been shown to translocate to the mitochondrial membrane after viral infection, where it associates with MAVS and promotes its oligomerization." (PMID 36876111, 2023). "QKI deficiency increases viral infection through the suppression of the host IFNβ response following the downregulation of the mitochondrial antiviral-signaling protein (MAVS), which is essential for innate immunity response against RNA virus infection." (PMID 37446229, 2023). "MAVS K63-linked ubiquitin moiety added on MAVS for its activation can be removed by YOD1 in the later stage of viral infection to restrain MAVS from overactivation." (PMID 35795661, 2022). "Among them, OTUD4 is induced in an IRF3/7-dependent manner, and OTUD1 increases the stability of MAVS during viral infection by directly removing the K48-linked ubiquitination of MAVS, thereby promoting RLR-mediated innate immune signals." (PMID 36505476, 2022). "The identification of Mitochondrial antiviral-signaling protein (MAVS) not only changed the conception of innate immune responses by viral infections, but also implicated a new role of mitochondria in innate immunity." (PMID 35223833, 2022). "TRIM31 also causes MAVS aggregation via K63-linked polyubiquitination, leading to the activation of MAVS after viral infection." (PMID 35008917, 2022). "The E3 ubiquitin ligase enzyme TRIM31, which is recruited to the mitochondria after viral infection to interact with MAVS, catalyzes the K63-linked polyubiquitination of MAVS at K10, K311, and K461 sites, promoting the oligomerization of MAVS." (PMID 36713387, 2022). "After viral infection, increased glucose metabolism and O-GlcNAc levels were found to be essential for O-GlcNAcylation and K63-linked ubiquitination of MAVS and for the initiation of downstream antiviral innate immune signaling in immune cells." (PMID 36056188, 2022). "Mechanistically, TRIM29 was shown to interacted with MAVS upon viral infection and to mediate its ubiquitination with at the K11-linked ubiquitin chains at K371, K420, and K500." (PMID 33808506, 2021). "We observed that MAVS of Usp18−/− MEF displayed significantly less K63-linked polyubiquitination following viral infection compared with that of Usp18+/+ MEFs." (PMID 34016972, 2021). "Endogenous co-IP experiments further verified that PB1 associated with MAVS following SZ19 virus infection at the indicated times." (PMID 33577621, 2021). "Viral infection leads to K63-linked ubiquitination of MAVS at the mitochondrial outer membrane, which in turn induces MAVS aggregation, a marker of its activation." (PMID 32536927, 2020).
viral infection (continued). "More recently, it was shown that the mitochondrial E3 ligase MARCH5 binds to MAVS aggregates during viral infection and conjugates K48-linked polyubiquitin chains at lysine residues 7 and 500, leading to their proteasomal degradation." (PMID 32117959, 2020). "YOD1, a deubiquitinase of the ovarian tumor family, is an MAVS interactor identified by coIP/MS that translocates to mitochondria upon viral infection to limit its activation through K63-linked deubiquitination." (PMID 32117959, 2020). "To find out the underlying mechanism by which MAVS is regulated upon viral infection, we tested the possible regulation role of miRNA for MAVS." (PMID 32678830, 2020). "Focal adhesion kinase (FAK) is an actin-associated tyrosine kinase that binds to MAVS in a viral infection-dependent manner and potentiates its signaling independently of its kinase activity." (PMID 32117959, 2020). "TRIM31 binds to inactive MAVS after viral infection and catalyzes the K63-linked polyubiquitination at Lys10, 311, and 461 to further promote aggregation of MAVS and thus enhance IFN-β production and antiviral signaling." (PMID 29872431, 2018). "It has been established that MAVS undergoes K48-linked ubiquitination during virus infection, which mediates MAVS degradation." (PMID 28594325, 2017). "Taken together, our study provides evidence showing that the H-Ras protein can enhance the assembly of the MAVS-associated signalosome upon viral infection in normal cells, thus exerting a positive role in antiviral activity." (PMID 28848563, 2017). "Our data thus reveal two essential polyubiquitin-mediated mechanisms underlying the activation of RIG-I and MAVS for triggering innate immune signalling in response to viral infection in cells." (PMID 28469175, 2017). "In this study, we aimed to analyse the association of MAVS single nucleotide polymorphisms (SNPs) with infectious diseases to assess the risk of viral infection based on MAVS variation." (PMID 26954674, 2016). "MAVS associated with mitochondria has the ability to induce both type I and III IFNs, while MAVS associated with peroxisomes selectively induces type III IFN production following viral infection in an IRF-1 dependent fashion." (PMID 28000722, 2016). "Having shown that expression of pexMAVS and mitoMAVS were able to induce type I and III IFN responses, we next compared these MAVS variants for their capacity to induce the IFN response upon viral infection." (PMID 26588843, 2015). "In HEK293T cells, virus infection causes mature gC1qR to migrate to the mitochondria where it associates with MAVS and thus prevents RIG-I/MDA-5 from interacting with this adaptor molecule." (PMID 24788809, 2014). "On the contrary, knockdown of endogenous MAVS blocks the induction of type I IFNs initiated by polyriboinosinic polyribocytidylic acid (poly I:C) or virus, leading to enhanced susceptibility to viral infection." (PMID 23249700, 2012). "Recent studies showed K63-linked ubiquitination of MAVS following viral infection modulates interaction with key components of the RIG-I signaling." (PMID 22844514, 2012). "This phenomenon is in stark contrast to the observations that loss of MAVS impairs cytokine production in response to viral infection, e.g., RNA viruses." (PMID 22110409, 2011). "To assess the role of immune signaling pathways downstream of cytosolic sensors in gamma herpesvirus infection, we have characterized viral infection and host innate immune responses in MAVS-deficient mice infected with γHV68." (PMID 22110409, 2011). "Notably, specific subdomains of mitochondrial-ER junctions, termed mitochondria-associated membrane (MAM), are crucial for MAVS signaling induction, and the disruption of MAMs by viral infection leads to a compromised antiviral immune response." (PMID 38338917, 2024). "So, shifted mitochondrial dynamics caused by viral infection can inhibit MAVS." (PMID 38338917, 2024).
viral infection (continued). "After depletion of DRP1 and FIS1 in cells, RLR signaling increases, and elongation of the mitochondrial network enhances the endoplasmic reticulum (ER)-mitochondria interaction during viral infection and increases the association of MAVS to enhance RLR signaling." (PMID 37692170, 2023). "Additionally, it is possible that the contribution of MAVS signaling in the clearance of CHIKV infection from cardiac tissue is associated with late steps of viral infection, potentially occurring after the systemic IFN-I response reaches negligible levels." (PMID 37537212, 2023). "Furthermore, MEF cells deficient in Wdr77 displayed increased MAVS aggregation upon viral infection, indicating a conserved inhibitory mechanism of WDR77 in antiviral signaling from mouse to human." (PMID 37563140, 2023). "Furthermore, RNF34 also catalyzes the K27- and K29-linked polyubiquitylation of MAVS at the K297/311/348/362 sites and clears mitochondria damaged by virus infection." (PMID 36498930, 2022). "Furthermore, E3 RNF5 also interacts with MAVS during viral infection, and it catalyzes K48-linked ubiquitination of K362 and K461 residues of MAVS, leading to its degradation by the proteasome." (PMID 36505476, 2022). "After the depletion of Drp1 and Fis1 in the cells, there is an increase in RLR signaling, and the elongation of the mitochondrial network promotes mitochondrial–endoplasmic reticulum interaction during the viral infection, enhancing the association of MAVS with a sting to augment RLR signaling." (PMID 34360945, 2021). "Third, immunoprecipitation followed by probing with K63-Ub specific antibody or TUBE assay against K63-specific linkages further strengthened the observation that deficiency of USP18 led to the decrease of K63-linked polyubiquitination of MAVS during viral infection." (PMID 34016972, 2021). "In addition, MAVS directly interacts with a translocase of the outer mitochondrial membrane 70 (TOM70) during viral infections, and TOM70 associates with HSP90." (PMID 32033216, 2020). "In addition, viral infection induces K27-linked ubiquitination and autophagic degradation of MAVS by MARCH8 and RNF34 in a NDP52-dependent manner." (PMID 33139700, 2020). "However, the relative contribution of mito- and pexMAVS to the induction of the antiviral state and counteraction of the MAVS variants by viral infection remains largely unexplored." (PMID 26588843, 2015). "In addition, we did not observe any cleavage of the upstream receptors NOD1 and NOD2, nor other crucial signaling proteins implicated in innate immune response to virus infection, including MAVS and STING." (PMID 26297639, 2015). "Viral infection induces large-prion like MAVS aggregates implicated in IRF3 activation." (PMID 23028469, 2012). "These protein complexes could then engage host protective innate immunity against viral infection via mitochondrial antiviral signaling protein (MAVS), a mitochondria-associated transmembrane protein, through their Caspase activation and recruitment domains (CARDs)." (PMID 38843304, 2024). "However, it is unknown how PCBP2 relocalizes to the cytosol where it associates with MAVS on virus infection." (PMID 26348439, 2015). "Viral infection can induce the activation of Drp1, thereby promoting mitochondrial fission and blocking the activation of the MAVS-mediated innate immune response." (PMID 40076578, 2025). "In this loop, ELF3 rapidly translocates to the nucleus to activate TRIM22 gene expression after viral infection, while TRIM22 activates IFN-β antiviral signaling through K63-linked polyubiquitination of MAVS." (PMID 40162781, 2025). "The ASK family is implicated in MAVS-dependent type I IFN production and apoptotic signaling during viral infections." (PMID 40837220, 2025).